BRAF (B-Raf proto-oncogene, serine/threonine kinase)
Diseases named in the same sentence as BRAF in open-access papers (continued):
Sharing a sentence is not in itself a finding about the gene and the disease.
melanoma (continued). "Somatic missense activating mutations in BRAF have been identified in about 60% of primary melanoma lesions, and KIT mutations in 14% and 18% of acral lentiginous and mucosal melanomas, respectively." (PMID 22281663, 2012). "In some MEK inhibitor-resistant melanoma cells which contained either the G469E or D594G mutant BRAF alleles, activation of Raf-1 by the mutant B-Raf proteins was observed to confer resistance to MEK inhibitors." (PMID 23085539, 2012). "A phase 2 trial involving patients who had received previous treatment for melanoma with the BRAF V600E mutation displayed a confirmed response rate of 53%, with a median duration of response of 6.7 months." (PMID 22333219, 2012). "The discovery that most human melanomas harbour mutations in either BRAF or NRAS has led to the development of targeted therapies, such as inhibitors of MEK or BRAF." (PMID 22475322, 2012). "Accordingly, mutations in BRAF are reported in up to 70% of cancer cell lines and they are highly prevalent in most common cancers with poor prognosis such as malignant melanoma." (PMID 23056577, 2012). "High incidence of activating mutations in the BRAF gene has been reported in melanoma cell lines, melanoma short-term cultures, primary and metastatic melanomas, and nevi." (PMID 22693489, 2012). "Switching from B-Raf to either Raf-1 or A-Raf was observed after incubation of melanoma cells containing the BRAF V600E mutation in the presence of the B-Raf inhibitor dabrafenib for prolonged periods of time in the recovered inhibitor-resistant cells." (PMID 23085539, 2012). "Around 60% of all melanomas express somatic mutations in the BRAF protein, and 90% of these express the oncogenic activating V600E mutation." (PMID 22216021, 2012). "The melanoma dependence on BRAF-mutated kinase allowed the development of inhibitors that produced major responses in clinical trials." (PMID 22216021, 2012). "BRAF and p16INK4 mutations, E-cadherin loss, and increased telomerase activity are frequently observed in melanoma cells." (PMID 21860617, 2012). "In fact, this significant hazard ratio for BRAF mutation in our study can indirectly explain the previously reported promising improvement of melanoma patient survival harboring BRAF mutation after selective BRAF inhibitor treatments." (PMID 23056577, 2012). "Directing this test to a single disease, 90 of 150 (60%) melanomas from sites throughout the body harbored a mutation tested, including 57, 23, 6, 3, and 2 mutations in BRAF, NRAS, GNAQ, KIT, and CTNNB1, respectively." (PMID 22536370, 2012). "Molecular analyses of melanomas have revealed an activated BRAFV600E mutation as a promising biomarker to test the efficacy of BRAF-targeted therapy in treating malignant melanoma." (PMID 22110486, 2012). "BRAF mutations are an attractive target for therapeutic interventions, as they represent an early event in melanoma pathogenesis and are preserved throughout tumor progression." (PMID 23209607, 2012). "p90RSK is required in mTORC1 activation in BRAF-mutated melanoma cells which leads to increased growth in vitro." (PMID 23216670, 2012). "The average prevalence of BRAF mutation was 9.6% in colorectal cancer, and 47.8% in melanoma reports." (PMID 23056577, 2012). "Although many patients with BRAF-mutated melanoma initially respond to vemurafenib, the only other agent approved by the FDA for this disease, most will ultimately relapse." (PMID 23228035, 2012). "For example, p16INK4 inactivation and BRAF mutation can accompany MITF amplification in melanoma cell lines, and ectopic MITF expression appears to work in synergy with BRAF mutation to transform primary human melanocytes." (PMID 22536322, 2012). "The BRAFV600E mutation accounts for >90% of BRAF mutations found in melanoma, and confers constitutive kinase activity." (PMID 22235286, 2012).
melanoma (continued). "The key regulatory role of BRAF mutation in MAPK activation especially in melanoma generated a tremendous research effort to block this signaling pathway for cancer treatment." (PMID 23056577, 2012). "Vemurafenib, an oral inhibitor of BRAF V600E mutated melanoma which occurs in approximately 50% of cases does however confer a survival advantage." (PMID 25562798, 2012). "It is possible that RAC1P29S and DCC loss cooperate in a manner similar to that of PTEN loss and mutations in BRAF or RAS in promoting melanoma tumor growth." (PMID 23372575, 2012). "Recently, it was demonstrated that the interaction of AKT with the mutated BRAF protein collaborates with melanoma development." (PMID 22216021, 2012). "Mutations in BRAF have been reported in up to 60% of melanoma cases, between 40 to 70% of thyroid carcinomas, and up to 18% of colorectal cancers." (PMID 23056577, 2012). "Oncologists and third party payers often focus on objective definitions of effectiveness and efficiency in specific clinical scenarios (e.g., impact of targeted treatment for BRAF V600E mutated melanoma on overall survival)." (PMID 25562407, 2012). "Summary of studies that evaluated the impact of BRAF mutation on overall patient survival in colorectal cancer and melanoma." (PMID 23056577, 2012). "In our meta-analysis, we combined the results of four independent studies and measured the pooled risk of BRAF mutation on melanoma patient survival." (PMID 23056577, 2012). "Then there is a plan for a test of the new Braf inhibitor Vemurafenib, shown to be effective in melanoma patients whose tumours display a mutation in BRAF V600E, but in colorectal patients instead of melanoma." (PMID 24883082, 2012). "Now imagine a panel of patients all of whom have melanoma with the BRAF V600E mutation and who receive vemurafenib; their data are aggregating in the informatics-enabled registry." (PMID 25562407, 2012). "A pool of studies published between 2002 and 2011 on the association between BRAF-V600E mutation and patient survival in colorectal cancer, malignant melanoma and papillary thyroid carcinoma were reviewed and analyzed for this study." (PMID 23056577, 2012). "Ras/Raf gain-of-function can occur through activation of ERK1 and ERK2, which are constitutively active in 70% of malignant melanoma due to RAS or BRAF activating mutations." (PMID 23316365, 2012). "In this study, by conducting meta-analysis on data reported in 30 independent studies, we evaluated the effect of BRAF-V600E mutation on patient survival in colorectal cancer and melanoma." (PMID 23056577, 2012). "Mutations in BRAF occur in 40%-60% of melanomas and 15%-30% of melanomas harbour activating NRAS mutations." (PMID 22475322, 2012). "Increased levels of AURKB have also been associated with activation of the MAPK pathway in melanoma, and furthermore application of the BRAF inhibitor vemurafenib, abrogated AURKB expression." (PMID 23110075, 2012). "BRAF mutations are observed in approximately 60-70% of malignant melanomas, 40% of thyroid carcinomas and 5-10% of colorectal cancers." (PMID 22994622, 2012). "These include pegylated interferon alpha-2b for stage III melanoma, vemurafenib for unresectable or metastatic melanoma with BRAF V600E mutation, and ipilimumab for treatment of unresectable or metastatic melanoma." (PMID 22333219, 2012). "Pooled log HR for BRAF mutation effect on patient survival in melanoma for cohort studies was 0.57 (0.35–0.80) and the final pooled log HR including one RCT was 0.53 (0.32–0.75) corresponding to a HR of 1.70 (1.37–2.12, 95% CI)." (PMID 23056577, 2012). "It has been shown to be effective when combined with dabrafenib in certain dabrafenib-resistant BRAF V600 melanoma lines that also had mutations at NRAS or MEK1." (PMID 23085539, 2012). "According to the Catalogue of Somatic Mutations in Cancer (COSMIC), approximately 42% of melanomas harbor BRAF mutations, of which 36% are V600E and 3% are V600R/K/M/G/D." (PMID 22536370, 2012).
melanoma (continued). "These small molecules have shown clinically meaningful activity in metastatic BRAF V600E mutated melanoma including patients with brain metastases." (PMID 22385786, 2012). "Nevertheless, the response rate of colon cancer patients harboring BRAF-V600E mutation to BRAF inhibitor treatment is much lower than melanoma patients." (PMID 23056577, 2012). "In contrast to the benign nevi, a high percentage of primary melanomas have concurrent mutations in BRAF and components of AKT pathway." (PMID 22880048, 2012). "BRAF is mutated frequently in melanomas (50-70%), papillary thyroid cancers (40%), Langerhans’-cell histiocytosis (57%)." (PMID 23006971, 2012). "Although the vast majority (>90%) of melanoma models harbored mutations in either BRAF or NRAS, significant differences in subcutaneous growth aggressiveness became obvious." (PMID 22535842, 2012). "This is supported by the observation that miR-146a, whose levels are higher in BRAF mutant cell-lines, is upregulated upon activation of the BRAF-encoded B-raf kinase protein in non-melanoma cells." (PMID 23209617, 2012). "In human melanomas expressing the BRAF mutation V600E, up-regulation of Snail1 was found to be inversely correlated with progression-free and overall survival of patients." (PMID 23173060, 2012). "BRAF inhibitor vemurafenib has shown remarkable clinical efficacy for the treatment of metastatic or unresectable melanoma with a BRAF V600E mutation." (PMID 22880048, 2012). "BRAF has taken center stage due to the discovery that it is mutated in prevailing human cancers, including 60% of malignant melanomas and 5%–15% of colon, ovarian, and thyroid carcinomas." (PMID 22870241, 2012). "An estimated progression free survival of 7 months was reported among all patients harboring the BRAF V600E mutation, which is present in approximately 50% of all melanomas." (PMID 23110092, 2012). "Subsequently, Phase III trial was conducted in 680 patients with previously untreated, unresectable stage IIIC or stage IV melanoma with BRAF V600E mutations." (PMID 22333219, 2012). "BRAF is frequently mutated in melanomas and certain other cancers and these mutations are frequently driver mutations." (PMID 23006971, 2012). "Unfortunately, a significant subset of melanomas and the majority of other tumors are initially BRAF-independent, while BRAF-mutated cancers eventually develop resistance in the course of therapy." (PMID 22869096, 2012). "In humans, NRAS and BRAF genes are mutated in 15% to 30% and in 50% to 70% of human melanomas, respectively, leading to their permanent activation followed by promotion of proliferation, survival, invasion, and angiogenesis of melanoma." (PMID 22013435, 2012). "As the BRAF gene is mutated in approximately 50 to 70% of melanomas, sorafenib was evaluated for its ability to suppress melanoma growth in mouse models." (PMID 23085539, 2012). "We focused our analysis on the effects of dacarbazine that was, until now, the reference treatment for metastatic melanoma and vemurafenib that recently proved efficiency in melanoma with BRAF V600E mutation." (PMID 22675422, 2012). "While NRAS mutations are observed in 15%–25% of melanomas, BRAF is mutated in as many as 50% of the cases." (PMID 22339359, 2012). "In a phase I/II study, after the escalation dose phase, 32 melanoma patients harboring the V600E BRAF mutation were included in the twice daily 960 mg dose regimen to evaluate response rate." (PMID 22216021, 2012). "BRAF is mutated in more than 50% of all melanomas, with BRAFV600E being the predominant mutation, increasing the protein's kinase activity and, thereby, driving downstream cellular proliferation through the MAPK pathway." (PMID 22651703, 2012). "DNA from fresh-frozen or FFPE human melanoma tissue was used to show detection of multiple BRAF V600 mutations V600E/K/M/R/E." (PMID 22536370, 2012).
melanoma (continued). "In patients with melanoma, the BEAMing platform has also been shown to detect BRAF mutations with a 75% concordance rate, although in the reported study, data were not available for up to a third of the tumor samples." (PMID 23144797, 2012). "It is notable that a large percentage of BRAF mutant melanomas also contain deletions or mutations in the PTEN gene." (PMID 22475322, 2012). "Among melanomas with mutated BRAF, the BRAFV600K mutation is observed in 12% of cases while BRAFV600R and BRAFV600D are each observed at a frequency of ∼5%." (PMID 23372575, 2012). "We examined five melanoma lines, three of which were BRAF- and two NRAS-mutated, and four colon carcinoma lines, of which three were KRAS- and one BRAF-mutated." (PMID 22869096, 2012). "Therapeutic BRAF inhibitors have shown clinically meaningful activity, particularly in metastatic BRAF V600E mutated melanoma including patients with brain metastases." (PMID 22385786, 2012). "We have tested a battery of melanoma and colon carcinoma cell lines that carry mutations in BRAF, NRAS and KRAS genes and have observed that those with NRAS and KRAS mutations are more sensitive to killing by IPA3." (PMID 22869096, 2012). "Vemurafenib displayed a relative reduction of 63% in the risk of death and of 74% in the risk of tumor progression in untreated, unresectable stage IIIC or stage IV melanoma with the BRAF V600E mutation, in comparison with treatment with dacarbazine." (PMID 22333219, 2012). "Mutational activation of BRAF, common in human melanomas, has been also associated with an enhanced IKK activity and a concomitant increase in the rate of IκBα ubiquitination and its subsequent degradation." (PMID 22433222, 2012). "We revealed that BRAF mutation is an absolute risk factor for patient survival in colorectal cancer and melanoma." (PMID 23056577, 2012). "The BRaf gain-of-function Val to Glu mutation is required for cell viability, anchorage-independent growth, and proliferation of BRafV600E-positive melanoma cell lines in both cell-based studies and in vivo mouse models." (PMID 22611400, 2012). "For such a disease, the BRAF inhibitors have recently been demonstrated to be effective on melanoma brain metastases harboring the V600EBRAF mutation." (PMID 22594466, 2012). "As a consequence, inhibitors of mutated BRAF are postulated to represent a therapeutic approach in LM from melanoma." (PMID 22594466, 2012). "We used 50 ng of DNA in the reactions, but it is likely that the CADMA assays will perform equally well using 25 ng or less DNA, which we have shown in a study of BRAF mutations in FFPE cutaneous malignant melanoma samples." (PMID 23173730, 2012). "Significant clinical benefits have been achieved using the RAF kinase inhibitor, vemurafenib, to treat melanomas showing BRAF mutations and the receptor protein kinase inhibitor, imatinib, to treat melanomas showing KIT mutations." (PMID 22281663, 2012). "Inhibition of BRAF signaling decreased NFκB promoter activity associated with survival, invasiveness and angiogenesis for melanoma formation." (PMID 22013435, 2012). "Today more than 75 somatic mutations in the BRAF gene have been identified in melanoma, and all mutations at V600 in Exon 15 constitutively activate BRAF." (PMID 21139585, 2011). "A phase-I trial (NCT00880321) of this oral compound enroled >100 patients with BRAF mutations (primarily melanoma patients)." (PMID 21139585, 2011). "In the past several years, the identification of mutations in the BRAF gene in melanomas has led to the development of molecular therapies targeting those mutations in metastatic melanomas, which is a highly lethal disease." (PMID 21911917, 2011). "This approach is supported by the dramatic success of PLX4032 for melanoma tumors possessing the BRAF V600E mutation, and Imatinib for those possessing C-KIT mutations." (PMID 21479172, 2011).
melanoma (continued). "We actually demonstrated a small population of melanoma cells harbouring activating BRAF mutations in a substantial number of tumours that were wild type by direct sequencing." (PMID 21224857, 2011). "Phase 1 and 2 clinical trials of the BRAF kinase inhibitor vemurafenib produced improved rates of overall and progression-free survival in patients with previously untreated melanoma with the BRAF V600E mutation." (PMID 22093436, 2011). "The recent advances in melanoma immunotherapy and molecular therapy directed against the activating mutation of BRAF have reenergized a field that now has many promising agents for which the benefits in combination with one another are a challenge to assess." (PMID 22220281, 2011). "The commonest BRAF mutation by far is T1799A (V600E), a T>A transversion present in more than 90% of all BRAF-mutated melanomas and naevi." (PMID 21827678, 2011). "The effects of PLX4032 were noted to be BRAF mutation specific, and equivalent responses were seen in melanoma models with both heterozygous and homozygous BRAF mutations." (PMID 21505227, 2011). "Although inhibition of MEK and ERK phosphorylation was achieved in BRAFV600E/K mutant melanoma, significantly increased tumour growth was seen in BRAF wild-type melanomas with upstream RAS mutations." (PMID 21139585, 2011). "The mitogen-activated protein kinase (MAPK) pathway is constitutively activated in approximately 90% of all melanomas, and new drugs targeting this pathway, e.g inhibitors of mutated BRAF or MEK, initially showed promising effects in vitro." (PMID 21915275, 2011). "In melanoma, BRAF mutations appear to enable immune evasion by suppressing the expression of melanoma differentiation antigens that typically serve as the targets for anti-tumor T cells." (PMID 24213115, 2011). "As a result, all patients with advanced melanoma should have BRAF mutational analysis prior to commencing systemic therapy." (PMID 22175026, 2011). "After the identification of BRAF mutations in a wide variety of human cancers, namely melanoma, ovarian carcinoma and microsatellite unstable colorectal carcinomas, we and others have reported a high prevalence (30% to 69%) of BRAF point mutations in PTC." (PMID 22654560, 2011). "For example, activating mutations in BRAF have been found to occur commonly in melanoma, and pimozide is more effective in tumors containing this mutation." (PMID 21680956, 2011). "Melanomas share initiating genetic alterations such as oncogenic mutations in BRAF and NRAS and often show recurrent patterns of chromosomal aberrations." (PMID 22190975, 2011). "Approximately 70–80% of acquired melanocytic nevi and 40–60% of malignant melanoma contain a BRAF mutation, the vast majority of which result in a single amino acid change at codon 600 (BRAFV600E)." (PMID 22175026, 2011). "BRAF mutation heterogeneity observed in the primary melanoma cell line MMG1 strongly supports this conclusion." (PMID 21224857, 2011). "Mechanistically it was noted that inhibition of BRAF in PTEN null melanoma cells was associated with an increase in phospho-AKT expression which led in turn to the decreased nuclear accumulation of FOXO3a." (PMID 21505227, 2011). "One such trial that is currently ongoing is a randomized, phase III trial of GSK1220212 compared with chemotherapy (either dacarbazine or paclitaxel) in patients with melanoma harboring BRAF mutations (NCIT01245062)." (PMID 22175026, 2011). "Although BRAF mutations are thought to be rare in acral and mucosal melanomas, primary tumours of these types of melanomas frequently contain minor populations of BRAF-mutant clones, which are likely to predominate in metastases." (PMID 21224857, 2011). "Molecular classification of melanoma is an emerging theme in melanoma therapeutics, with BRAF and c-KIT mutation status determining novel treatment options." (PMID 21980408, 2011).